FAM53B (family with sequence similarity 53 member B)
Description:
Acts as a regulator of Wnt signaling pathway by regulating beta-catenin (CTNNB1) nuclear localization.
Synonyms: KIAA0140; SMP; bA12J10.2
Tractability: PROTAC: ubiquitination databases record sites on it.
Gene: Protein-coding gene on chromosome 10 (124,619,292 to 124,744,475, reverse strand). Ensembl gene ENSG00000189319.
Subcellular location: Nucleus
Subcellular location (Human Protein Atlas): Cytosol
Gene Ontology:
Molecular function: protein binding
Biological process: positive regulation of canonical Wnt signaling pathway; regulation of canonical Wnt signaling pathway; protein import into nucleus
Cellular component: nucleus
Genetic constraint (gnomAD): Loss-of-function variants: 12 observed, 34.25 expected, observed/expected ratio (o/e) 0.35, 90% interval 0.22 to 0.57. The upper end of that interval is the gene's LOEUF score, 0.57, which puts it in group 2 of 6, group 1 being the genes least tolerant of losing a copy. Missense variants: 477 observed, 585.19 expected, observed/expected ratio (o/e) 0.82, 90% interval 0.75 to 0.88. Synonymous variants: 234 observed, 232.74 expected, observed/expected ratio (o/e) 1.01, 90% interval 0.9 to 1.12.
Homologues: Orthologues: macaque FAM53B (98% identical), guinea pig FAM53B (87% identical), pig FAM53B (86% identical), rabbit FAM53B (86% identical), mouse Fam53b (86% identical), rat Fam53b (85% identical), dog FAM53B (81% identical), chimpanzee FAM53B (75% identical), zebrafish fam53b (37% identical). Paralogues in human: FAM53A (25% identical), FAM53C (25% identical).
Diseases named in the same sentence as FAM53B in open-access papers:
FAM53B is named in the same sentence as 11 diseases in open-access papers, as found by Europe PMC text mining. Sharing a sentence is not in itself a finding about the gene and the disease. The quoted sentences say what the papers report.
multiple myeloma (2 papers, 2017 to 2021). "FAM53B has also been identified as a critical gene in the prognosis of multiple myeloma in a transcriptional network analysis." (PMID 28179588, 2017).
pancreatic cancer (2 papers, 2021 to 2022). "With the help of qRT-PCR, the expression levels of FAM53B in human pancreatic cell line and four distinct pancreatic cancer cell lines were detected." (PMID 34717651, 2021).
acute lymphoblastic leukemia (1 paper, 2020). Leukemia with an acute onset, characterized by the presence of lymphoblasts in the bone marrow and the peripheral blood. "In acute lymphoblastic leukemia (ALL) cells, the FAM53B fusion transcript could code a truncated FAM53B protein, which was considered to be of great biological significance because of its entire conserved domain, even though the mechanism was unclear." (PMID 33344452, 2020).
asthma (1 paper, 2023). "Some of these sites were associated with offspring outcomes in this cohort including ever-asthma (NTRK2), ever-wheezing (DNAJC14, TPCN1), weight (FAM53B, NTRK2) and BMI (FAM53B, NTRK2) (p < 0.05)." (PMID 37649101, 2023).
breast carcinoma (1 paper, 2017). "FAM53B is required for Wnt signaling, a pathway involved in epithelial-to-mesenchymal transition and subsequent metastasis in breast cancer." (PMID 28179588, 2017).
cancer (3 papers, 2021 to 2023). A tumor composed of atypical neoplastic, often pleomorphic cells that invade other tissues. "ARHGAP26 and FAM53B were found associated with five cancer types, and PIP5K1C, FBP1, and CUL9 were found to be associated with four cancer types." (PMID 37187613, 2023). "The results indicated that the mRNA levels of ANLN, ARNTL2, CDKN3, and FAM53B in the cancer cell lines (SW 1990, BxPC-3, CFPAC-1, and PANC-1) were significantly higher than those in the normal cell line (HPDE), indicating their prognostic value." (PMID 35864471, 2022). "In addition, the expression levels of ANLN, ARNTL2, CDKN3, and FAM53B were upregulated in cancer tissues from our cancer center." (PMID 35864471, 2022).
tumor (1 paper, 2021). "Subsequently, correlation of FAM53B with immunotherapeutic hub genes adjusted by tumor purity to explore the biological role of FAM53B in immunotherapy." (PMID 34717651, 2021). "The expression levels of FAM53B were between tumor samples and normal tissues according to TCGA and GTEx datasets." (PMID 34717651, 2021). "For tumor tissues and normal specimens, FAM53B expression value exhibited a higher trend in tumor tissues." (PMID 34717651, 2021). "The results showed that relative to normal samples, proteins (ABCB4, FAM53B, and INTU) were significantly dysregulated in tumor tissues." (PMID 34717651, 2021).
FAM53B also shares sentences with these, for which no sentence is quoted: ovarian carcinoma (2 papers); cocaine dependence (1); dementia (1); neurodegenerative disease (1).